SIRPA (signal regulatory protein alpha)
Diseases named in the same sentence as SIRPA in open-access papers (continued):
Sharing a sentence is not in itself a finding about the gene and the disease.
peritonitis (1 paper, 2015). Inflammation of the peritoneum (tissue that lines the abdominal wall and covers most of the organs in the abdomen). "During thioglycolate-induced peritonitis in SIRPα mutant mice, both neutrophil and macrophage influx were found to occur, but to be significantly delayed." (PMID 26057870, 2015).
prion disease (1 paper, 2017). A transmissible disease that is caused by a protein that is able to induce abnormal folding of normal cellular proteins, leading to characteristic spongiform brain changes, which are associated with neuronal loss without an inflammatory response. "Besides disease incubation, we explored whether ablation of a functional SIRPα-dependent signaling would impact on histologic and biochemical hallmarks of prion diseases." (PMID 28545141, 2017). "Collectively, these data indicate that SIRPα-mediated phagocytosis is not a major determinant in prion disease pathogenesis." (PMID 28545141, 2017).
psoriasis (1 paper, 2024). An autoimmune condition characterized by red, well-delineated plaques with silvery scales that are usually on the extensor surfaces and scalp. "To determine the causal role of small intestinal eosinophil degranulation in psoriasis, we generated eosinophil-specific SIRPα conditional knockout mice (EpxCre/+Sirpafl/fl) and treated them with IMQ." (PMID 38689088, 2024).
rectal tumors (1 paper, 2023). "SDR16C5 has been found to be upregulated in KRAS-mutant rectal tumors compared to KRAS wild-type, and increased SIRPA may be indirectly linked to mutant KRAS through the overexpression of the EZH2 polycomb complex." (PMID 37141389, 2023).
Salmonella Infections (1 paper, 2024). Infections with bacteria of the genus SALMONELLA. "However, mice with SIRPα deficiency showed increased susceptibility to S. typhimurium infection, indicating that SIRPα may contribute to host defense against Salmonella infection." (PMID 38933265, 2024).
scleroderma (1 paper, 2025). Scleroderma is a rare autoimmune connective tissue disorder characterized by abnormal hardening of the skin and, sometimes, other organs. "The disruption of CD47 receptor and SIRPα agonist interaction to enhance macrophage functions (including phagocytosis, antigen presentation, and ADCC) has shown promise in scleroderma." (PMID 40299362, 2025).
skin cutaneous melanoma (1 paper, 2024). "Lastly, we evaluated the correlation between HDAC6 expression and SIRPα expression in skin cutaneous melanoma (SKCM) patients utilizing Gene Expression Profiling Interactive Analysis (GEPIA), a server for interactive analysis of normal and cancer expression profiles." (PMID 38414061, 2024).
Splenomegaly (1 paper, 2023). Abnormal increased size of the spleen. "As in the antibody model, JAK2 mutant mice developed pronounced splenomegaly, which was not accentuated on the mutated Sirpα background." (PMID 37095207, 2023).
temporal lobe epilepsy (1 paper, 2011). A localization-related (focal) form of epilepsy characterized by recurrent seizures that arise from foci within the temporal lobe, most commonly from its mesial aspect. "SIRPA is involved in negative regulation with numerous growth factor signaling receptors; and PDYN has been found to be associated with nonlesional temporal lobe epilepsy, but results have not been replicated." (PMID 21223598, 2011).
tuberculous meningitis (1 paper, 2012). "Those described previously included signal-regulatory protein alpha (SIRPA) and protein disulfide isomerase family A, member 6 (PDIA6), which have been shown to be overexpressed at the mRNA level in tuberculous meningitis." (PMID 23198679, 2012).
uveitis (1 paper, 2021). An inflammatory process affecting a part of or the entire uvea. "Recently CD47-signal regulatory protein alpha (SIRPα) interactions have been implicated in induction of T cell-mediated inflammation, and thus we sought to assess the role of this signaling axis in a pre-clinical model of uveitis that is largely driven by T-cell activation." (PMID 34093583, 2021).
tumor (873 papers, 2012 to 2026). "Recent studies revealed that SIRPA deficiency reprogrammed tumor-associated macrophages toward an antitumor phenotype, and SIRPA functioned independently of CD47." (PMID 42116089, 2026). "Macrophages deficient in SIRPα lead to enhanced anti-tumor effects; however, how efficiently gene manipulations can be made in patient macrophages for therapy has not yet been shown." (PMID 40082557, 2025). "One strategy to combine the benefits of a tumor-restricted CD47 blockade with a pro-phagocytic stimulus in a single molecule is to fuse SIRPα with a tumor-associated antigen (TAA)-specific IgG1 antibody." (PMID 40402266, 2025). "In this system, GM-CSF–loaded OMVs primed bone marrow progenitors and monocytes, which were later recruited to the tumour site by tumour-associated macrophages (TAMs), while SIRPα-Fc–modified OMVs improved TAM-mediated phagocytosis." (PMID 40733744, 2025). "We then map the specific treatments of SIRPα-CD47 inhibition for MC38 tumor cells in WT and SIRPα-deficient mice according to their phagocytosis values (φm) as cross-sections through the 3D space." (PMID 41296731, 2025). "In this study, a modified oAdV vector, pDC316-oAd-SA, was engineered to express the SIRPα-mIgG1Fc gene, designed to remodel tumor-associated macrophages (TAMs) and enhance anti-tumor immunity." (PMID 40070841, 2025). "Pre-clinical studies showed that BR105 binds to various SIRPα variants, synergizes with therapeutic antibodies to promote phagocytosis, and inhibits tumor growth in vivo." (PMID 40700292, 2025). "SIRPA blockade restricted the development of liver metastases in Clec4fcreId3f/f mice, and rescued the phagocytosis of tumour cells by Id3-deficient KCs to wild-type levels in vivo and in vitro." (PMID 38326607, 2024). "For example, SIRPα was associated with the tumor-polarized macrophage phenotype and inflammatory state." (PMID 39696410, 2024). "For example, nanovesicles carrying a fusion protein composed of SIRPα and PD-1 variants on their surface effectively induce anti-tumor immunity of T cells and macrophages." (PMID 38903499, 2024). "Tumor-associated macrophages express the signal-regulatory protein α (SIRPα) and the thrombospondin-1 which interact with the CD47 receptor, a don’t eat me signal, expressed by tumor cells and tumor-associated ECs." (PMID 38426109, 2024). "Studies have shown that macrophages deficient in SIRPα exhibit heightened cytophagocytic activity and enhanced anti-tumor immunity compared to wild type." (PMID 39160226, 2024). "Specifically, CD47 interacts with SIRPα on tumor‐associated macrophages, inhibiting macrophage‐mediated phagocytosis and promoting immune evasion." (PMID 39297408, 2024). "CD47, a small molecule expressed on the surface of tumor cells, functions as a “don’t eat me” mark by binding to signal-regulatory protein alpha (SIRPα), an inhibitory receptor, on tumor-associated macrophages (TAMs) and dendritic cells (DCs)." (PMID 38560565, 2024). "Accumulating researches had shed light on the synergistic effects of SIRPα blockade and other agents, such as tumour‐associated antigens and immune checkpoint inhibitors." (PMID 36419386, 2023). "That study also demonstrated that preventing CD47/SIRPα cross-talk causes a variety of polarized macrophages to engulf tumor cells and that this action is necessary for producing FcγRs." (PMID 38033495, 2023). "Secondly, blocking the CD47/SIRPα axis can transform tumor-associated macrophages into an antitumor state, and increase tumor macrophage recruitment." (PMID 36726125, 2023). "The use of anti-CD47 mAbs reduces CD47/SIRPα cross-talk, thereby causing macrophages to phagocytose tumor cells." (PMID 38033495, 2023). "Interaction of tumour PD‐L1 with PD‐1 on tumour infiltrating lymphocytes (TILs) and tumour CD47 with SIRPα on tumour‐associated macrophages (TAMs) have been recognised as a major mechanism of tumour immune evasion." (PMID 37974395, 2023).
tumor (continued). "CD47 is identified as an integrin‐associated protein on tumor cells and binds to signal regulatory protein alpha (SIRPα) on phagocytes, such as macrophages." (PMID 36598153, 2023). "Exosomes with SIRPα on their surface have been constructed capable of preventing CD47-SIRPα interaction between cancer cells and macrophages, causing tumor growth to regress." (PMID 37373342, 2023). "In the late 2000s, the cross talk of CD47/SIRPα was recognized as the first checkpoint associated with tumor phagocytosis (also known as a “don’t eat me” signal)." (PMID 35978372, 2022). "BR105 is a differentiating anti-SIRPα antibody that binds to major SIRPα variants and activate macrophages to lead enhanced phagocytosis of tumor cells." (PMID 35256517, 2022). "Kaplan–Meir survival analysis of disease-specific survival (considering all cases) showed a direct association of high SIRPα/CD68-ratio in inner tumor areas with poor prognosis (p = 0.02)." (PMID 35406573, 2022). "Immunotherapies targeting the “don’t eat me” myeloid checkpoint constituted by CD47 SIRPα interaction have promising clinical potential but are limited by toxicities associated with the destruction of non-tumor cells." (PMID 35795660, 2022). "CD47 is overexpressed on a variety of tumor cells and activates “don’t eat me” signaling by binding to SIRPα, causing immune escape of tumor cells from the mononuclear phagocyte system." (PMID 35890175, 2022). "In some human cancers, CD47 binds to SIRPA to trigger the inhibitory signaling pathway that caused tumor cells to evade from phagocytosis by macrophages." (PMID 35211415, 2022). "A reduction in the CD47/SIRPα signaling pathway via PD-1 blockade significantly reduced tumor growth by downregulating tumor immune-suppressive network mediators, such as MDSCs, tumor-associated macrophages, DCs, as well as effector T cells." (PMID 36233088, 2022). "EVs harboring SIRPα variants (SIRPα-exosomes) were sufficient to induce remarkably augmented phagocytosis of tumor cells by macrophages and increased CD8+ T cell TME infiltration." (PMID 36498469, 2022). "CD47, an integrin-associated protein that is overexpressed in malignant tumor cells, functions as an inhibitor of macrophage-mediated phagocytosis through the ligation of SIRPα." (PMID 33802565, 2021). "For example, ADU-1805, an anti-SIRPα monoclonal antibody, generated to block all known SIRPα alleles to excel anti-tumor activity across SIRPα variants, demonstrated in vitro and in vivo activity." (PMID 34944850, 2021). "SIRPα-deficient macrophages activated by irradiated tumor-released DAMPs exhibit robust efficacy and orchestrate an anti-tumor response that controls late-stage tumors." (PMID 34050181, 2021). "CRCs contained various numbers of tumor-associated immune cells (TAIs) with SIRPA, CD68, or CD163 expression." (PMID 33799989, 2021). "The authors in this study demonstrated that SIRPα-deficient macrophages gained potent anti-tumor properties and coordinated a robust immune response when delivered in combination with radiotherapy." (PMID 34899748, 2021). "Within the immune cell compartment, SIRPα was primarily expressed by dendritic cells (DCs), mainly the type 2 conventional (cDC2) subset, monocytes and tumor-associated macrophages (TAMs)." (PMID 34917090, 2021). "SCLC tumors present RNA levels for macrophage markers (including SIRPα), and their analysis show a positive association between macrophage infiltration and tumor stage." (PMID 34195295, 2021). "Anti-MUC1 and anti-EGFR (cetuximab) antibodies have achieved effective antitumor effects in carcinoma A549 cancer cells, causing tumor regression by inhibiting the binding of SIRPα and CD47." (PMID 34683963, 2021). "Here the authors show that hybrid cellular membrane nanovesicles loaded with a STING agonist or overexpressing high-affinity SIRPα variants can be exploited to promote anti-tumor immune responses." (PMID 32999291, 2020).
tumor (continued). "Here we found that Shp1 bound to phosphorylated peptide sequences derived from SIRPα and transduced the anti-phagocytic signal, as Shp1 loss in mouse bone marrow-derived macrophages increased phagocytosis of tumor cells in vitro." (PMID 33133093, 2020). "In different CRC models, the expression of the inhibitory immune checkpoint receptor Sirpα in TAM increases during tumor progression, in association with impaired phagocytosis of tumor cells." (PMID 32962159, 2020). "Exosomes harboring SIRPα variants (SIRPα-exosomes) were sufficient to induce augmented tumor phagocytosis, resulting in a prime, effective anti-tumor T cell response." (PMID 32746880, 2020). "Treatment of tumour-bearing mice with exosomes harbouring SIRPα variants have led to intensive infiltration of CD8+ T cells in the tumour microenvironment, as well as subsequent inhibition of tumour growth." (PMID 32276342, 2020). "Taken together, these results indicate that CD11c+SIRPα+ DCs play an essential role in the antitumor responses induced by CD47-deficient tumor cell vaccination." (PMID 31996683, 2020). "RRx-001 switches the macrophage phenotype from M2 to M1 and causes a decrease in expression of SIRPα and enhanced tumor clearance by macrophage phagocytosis in vivo." (PMID 33552071, 2020). "RRx-001 is a minimally toxic small molecule that dually downregulates CD47 on tumor cells and SIRPα on macrophages and triggers tumor associated macrophage phagocytosis of tumor cells in vitro and in vivo." (PMID 30400835, 2018). "Human tumors grown in immunodeficient NOD-SCID mice that express a variant of SIRPα that binds human CD47 with high affinity have been used to test the ability of B6H12 to enhance macrophage-mediated clearance of human tumor xenografts." (PMID 26840086, 2016). "Elevated CD47 expression limits the killing of tumor cells through its interaction with SIRPα, whereas loss of CD47 triggers phagocytosis." (PMID 27671753, 2016). "A recent report indicates that CD47/SIRPα axis plays an important role by reducing mature DCs and attracting tumor associate macrophages." (PMID 26573233, 2015). "To elucidate the mechanisms underlying tumour immune evasion and guide the design of targeted interventions, we first performed comprehensive pathway enrichment and network analyses focused on genes functionally associated with PD-L1 and SIRPα/CD47 signalling." (PMID 41402667, 2025). "SIRPA/Sirpα elevated levels are associated with tumor progression, as genetically engineered SIRPA−/− mice were demonstrated to have developed smaller subcutaneous MC38 tumors and exhibited prolonged survival, while rechallenged tumors were completely rejected." (PMID 41450739, 2025). "Further validation through functional cellular experiments is planned, including spatial and temporal studies of tumor-associated macrophages through tracing techniques after irradiation and further examination of the antigen-presenting functions of SIRPα + macrophages in different types of cancers." (PMID 40208335, 2025). "Therefore, radiotherapy combined with CD47/SIRPα axis-associated immunotherapy can further promote anti-tumor efficiency, which is mainly associated with reshaped immune-activated irradiated tumor microenvironments." (PMID 40835598, 2025). "This discrepancy may be attributable to the observation that CD47‐mediated immune evasion is contingent on its interaction with SIRPA on tumor‐associated macrophages." (PMID 41354057, 2025). "We therefore reasoned that ID3 may regulate the inhibitory/activating receptor balance in macrophages, and that the control of SIRPA and dectin-1 expression may underlie at least part of the anti-tumour activities of wild-type KCs." (PMID 38326607, 2024). "The amount of tumor-cell debris engulfed by myeloid cells also increased upon SIRPα blockade, actively showing that SIRPα blockade enhances both the number of tumor-associated myeloid cells sampling material and the phagocytic capacity of individual cells in vivo." (PMID 38577107, 2024).
tumor (continued). "Previous researches suggested that nanovesicles (NVs) overexpressing high‐affinity PD‐1 or SIRPα variants, which could push the limit of current therapeutics, significantly alleviated the immunosuppressive state of tumour and delayed tumour growth." (PMID 37974395, 2023). "In the mouse tumor model, administering tumor-opsonizing antibodies with inhibition of this phagocytosis checkpoint promoted therapeutic efficacy, and SIRPα-deficient macrophages showed activation of cytotoxic T cells by conducting immunogenic antigen presentation." (PMID 36626230, 2023). "Thus, we conclude that SIRPα deficiency protected mice from tumour growth, dependent on the presence of MPs and NPs." (PMID 36419386, 2023). "We hypothesized that the abundant immunogenic adjuvants in bacterial lysis (e.g., flagellin) may lead to the reduced surface expression of SIRPα on tumor-associated macrophages." (PMID 36959204, 2023). "Resistance to ADCP may also occur through the overexpression on MM cells of CD47, which binds to SIRPα on tumor‐associated macrophages (TAMs) and contributes to the immune escape of tumor cells by inhibiting ADCP." (PMID 37840445, 2023). "In addition, the expression of Siglec10 and SIRPα had strong associations with macrophages while TIGIT had weak associations with macrophage among almost all tumor types." (PMID 38016957, 2023). "An important signal system is the CD47/signal regulatory protein alpha (SIRPα) pathway, which is the target for several inhibitory drugs that are currently being investigated in clinical trials including soluble variants of SIRPα to outcompete macrophage binding to CD47 on the tumor-cells." (PMID 35883493, 2022). "Moreover, we analyze the association of CD47/SIRPα with the PD-L1/PD-1 axis and with parameters related to tumor-infiltrating lymphocytes." (PMID 35406573, 2022). "The results demonstrate that SIRPα is a master regulator underlying tumor resistance to RT and provide proof-of-principle for SIRPα-deficient macrophage-based therapies to treat a broad spectrum of cancers, including those at advanced stages with low immunogenicity and metastases." (PMID 34050181, 2021). "Here the authors show that, in preclinical cancer models, resistance to radiotherapy (RT) observed in wild-type mice is overcome in Sirpα-deficient mice, providing evidences that RT-activated Sirpα-deficient macrophages promote T-cell mediated anti-tumor immune responses." (PMID 34050181, 2021). "Unexpectedly, SIRPα variants are insufficient in inducing macrophage phagocytosis as single agents, but could serve as adjuvants to specific antibodies that opsonize tumor cells for destruction." (PMID 32999291, 2020). "However, in this study, the engineered SIRPα variant was designed so as to combine with the oncolytic adenovirus owing to its high specificity for tumor cells and ability to lyse targets while sparing normal cells." (PMID 31899582, 2020). "The SIRPα-extracellular vesicles-mediated CD47 blockade causes tumor growth inhibition." (PMID 29850495, 2018). "To locally interfere with the CD47-SIRPα axis at the tumor site, we generated the so-called local inhibitory checkpoint monoclonal antibodies (licMABs), which consist of the endogenous SIRPα V-like domain linked to a mAb targeting CD33, a validated target antigen in AML." (PMID 28061465, 2017). "It is important to note that targeting tumor cells with CD47-specific blocking antibodies or soluble signal regulatory protein-α (SIRPα) variants inhibits CD47- SIRPα interaction and facilitates tumor cell removal by macrophages, leading to reduction tumor growth and metastasis." (PMID 29348826, 2017). "Therefore, potential blockade of SIRPγ may result in the inhibition of tumor-associated T cells, which would reduce the therapeutic effect of SIRPα targeting antibodies." (PMID 40408355, 2025).